PIK3CA (phosphatidylinositol-4,5-bisphosphate 3-kinase catalytic subunit alpha)
Diseases named in the same sentence as PIK3CA in open-access papers (continued):
Sharing a sentence is not in itself a finding about the gene and the disease.
tumor (continued). "DNA isolated from archival-tumor tissue samples was analyzed to identify PIK3CA somatic mutations." (PMID 28330468, 2017). "PIK3CA mutations were also commonly found, although the mutated position in the gene was different between the recurrent and the primary tumor, indicating that convergent evolution had occurred in the course of tumor growth." (PMID 28270234, 2017). "In four patients (I, IX, X, XLVII) CTCs harboring PIK3CA hotspot mutations could be observed as well as tumor cells carrying the WT form of the gene." (PMID 28858218, 2017). "Activating mutations in PIK3CA were present in ∼31% of BRCA tumours and 20% of HNSC tumours." (PMID 28139702, 2017). "More importantly, the luminal-A tumor patients harboring the PIK3CA mutation and this positively regulating loop in their tumors have significantly longer survival than those whose tumors containing PIK3CA mutation only." (PMID 28392480, 2017). "Somatic gain-of-function mutations in the coding region of both PI3K subunit genes, PIK3R1 (coding for p85α, the regulatory subunit of isoform α class I PI3K heterodimer) and PIK3CA (encoding the p110α catalytic subunit), are commonly found in many tumor types." (PMID 28143957, 2017). "According to the authors, PIK3CA mutation quantification correlated with changes in tumor burden." (PMID 28330468, 2017). "More investigation of the molecular mechanisms of the FFL (PDGF/FLT1/SHC1) in the PIK3CA-mutated luminal-A tumor patients could lead to better predictions and more personalized treatment." (PMID 28392480, 2017). "Our results indicate that patients who receive neoadjuvant TCHL and have PIK3CA/ERBB family mutated tumours may be more likely to have a pCR than patients with WT tumours." (PMID 28750640, 2017). "However, in the TCHL (but not the TCH) group, the pCR rate was higher for 9 patients with PIK3CA/ERBB family mutated tumours than for 20 patients with PIK3CA/ERBB family WT tumours (77.8% vs. 35%; p = 0.05)." (PMID 28750640, 2017). "Six PDXs, representing 20.8% of the tumours in this study, harboured druggable somatic mutations, including PIK3CA p.H1047R and KRAS p.A146V in WHIM9, PIK3CA p.H1047R in WHIM16 and WHIM24, PIK3CA p.E545K in WHIM18, PIK3CA p.E542K in WHIM20 and SF3B1 p.K700E in WHIM26." (PMID 28348404, 2017). "The study concluded that tumours with PIK3CA mutations exhibit Akt dependency when there is manifestation of defective feedback regulation or phosphate and tensin homolog (PTEN) signaling, whereas they exert Akt- independent signaling and they recruit SGK3 when such deficiencies are absent." (PMID 29064423, 2017). "Additionally, some other factors, such as different study design (prospective versus retrospective), tumor KRAS/BRAF/PIK3CA mutation status that affected the survival of CRC patients should also be attributed to some of the heterogeneity." (PMID 28977964, 2017). "The hypothesis is that FFL positively-regulating motifs exist in the subset of luminal A tumor samples harboring the PIK3CA mutation that may be involved the cancer process." (PMID 28392480, 2017). "In this study, we have tested the feasibility of array-based digital PCR to detect and quantify tumor specific mutations in plasma samples and we have documented the correlation between PIK3CA mutation quantification and tumor responses assessed by RECIST criteria." (PMID 28330468, 2017). "Multivariate analysis indicated that pathological grade and tumor size at diagnosis were positively associated with PIK3CA mutations, which indicates that cancers with PIK3CA mutations may be more invasive." (PMID 28729728, 2017). "Likewise, tumours with combined mutations in exons 9 and 20 of PIK3CA have a worse outcome than tumours harbouring just one of those mutations." (PMID 28106826, 2017). "Interestingly, PIK3CA mutations were significantly associated with lower tumor grade, lower S-phase fraction, and reduced Ki67 staining." (PMID 27484095, 2016).
tumor (continued). "This pathway can be targeted by various means, which may provide potential selective therapies for the treatment of the large number of patients whose tumours harbour PIK3CA mutations." (PMID 27321283, 2016). "Another activating mutation of PIK3CA gene was found in the recurring tumor." (PMID 26943575, 2016). "All this suggests that the reduction by aspirin may be restricted to patients whose tumours show mutation in PIK3CA, HLA class I antigen, or show COX-2 over-expression." (PMID 27096951, 2016). "Importantly, PIK3CA mutations have been associated with favorable clinicopathological parameters, i.e. ER expression, smaller tumor size and low histological grade, as well as good prognosis." (PMID 27129168, 2016). "Our results suggests that cervical cancer patients whose tumours are positive for the PIK3CA-E545K mutation may benefit from PI3K inhibitor therapy in concert with standard cisplatin and radiation therapy." (PMID 27489350, 2016). "While alterations in PIK3CA may act as driver mutations in some tumours, they could also act as passenger mutations in others." (PMID 27765909, 2016). "We next tested if GPT2 expression is upregulated in CRC tumour specimens with PIK3CA mutations." (PMID 27321283, 2016). "However, the prevalence of functional PIK3CA mutations was similar between the two groups (HER2+/ER+=29.5%, HER2+/ER−=30.1%), although there were significantly fewer PIK3CA mutations in HER2+/ER+ tumours than in HER2−/ER+ tumours (46.5%)." (PMID 27161491, 2016). "Eventually, new prospective trials combining celecoxib with hormone therapy or chemotherapy may screen patients for tumor PIK3CA mutations to confirm its predictive value." (PMID 27835884, 2016). "Among the 125 patients, 105 tumor samples were available for PIK3CA mutation analysis." (PMID 27016421, 2016). "Emerging data suggest that tumour PIK3CA mutation status, expression of cyclo-oxygenase-2 and human leukocyte antigen class I, along with certain germline polymorphisms, might all help to identify individuals who stand to gain most." (PMID 27069437, 2016). "Mutations in PIK3CA have been observed in up to 27% of GBM tumor samples." (PMID 27120806, 2016). "Interestingly, PIK3CA mutations correlated with lower tumor grade (P = 0.0265) and lower S-phase fraction (P = 0.0416)." (PMID 27484095, 2016). "Although not all tissue variants could be confirmed in the matched serum, up to 57% of the tumor variants were reflected in matched cfDNA with mutations in PIK3CA, ALK, and PTEN as well as variants at COSMIC annotated sites in all six patients analyzed." (PMID 27529345, 2016). "Furthermore, if PIK3CA mutation(s) caused resistance to EGFR TKI, the cancer cells with PIK3CA mutation would proliferates with tumor progression; therefore the population of PIK3CA mutant cells would increase and not be in low percentage mosaicism." (PMID 27734950, 2016). "On the other hand, activating PIK3CA mutations make the tumours refractory to ErbB2-targeted therapy, and the response may be restored by co-inhibition of PI3K." (PMID 27255951, 2016). "In particular, EBV-positive tumours have a strong predilection for PIK3CA mutations." (PMID 27514667, 2016). "They reported PIK3CA mutations facilitate tumor invasion and attenuate apoptosis." (PMID 27242542, 2016). "In our set of samples, Tumor #1 and Tumor #3 carried mutations in PIK3CA, with variant allele frequencies of 38% and 26%, and Tumor #4 harbored an NF1 mutation, which might activate the PI3K signaling pathway." (PMID 27057633, 2016). "High correlation was noted in the PIK3CA mutation status between tumour gDNA and serum cfDNA." (PMID 26498688, 2015).
tumor (continued). "Also, PTEN loss increases tumor cell susceptibility to PI3K inhibition compared to PIK3CA mutations." (PMID 26452060, 2015). "Of the 5 tumor pairs that had mutations before and after chemotherapy (MT→MT subgroup), the pre and post-chemotherapy mutations were identical in each tumor, and all mutations were in PIK3CA (H1047R n = 2; E542K n = 1; E545K n = 1; N345K n = 1)." (PMID 26630576, 2015). "We hypothesize that combined mutations might be the consequence of sequential waves of mutations during clonal cell expansion, but it is also possible that PTEN loss and PIK3CA mutation might be responsible for different pathologic events in tumor progression." (PMID 26540293, 2015). "Of the 38 tumour samples analysed, only two samples were positive for PIK3CA mutations." (PMID 26498688, 2015). "Notably, no recurrence occurred for the three patients in the CIT cohort whose tumor harbored concomitant PIK3CA exon 9 and exon 20 mutations." (PMID 25641861, 2015). "In addition, testing of cfDNA demonstrated acceptable concordance (BRAF, 91%; EGFR, 99%; KRAS, 83%; PIK3CA, 91%) with standard of care mutation analysis of primary or metastatic tumor tissue obtained during clinical care." (PMID 25980577, 2015). "Indeed, the feasibility of assessing PIK3CA mutation in circulating tumor cells and circulating free DNA has already been demonstrated." (PMID 25857348, 2015). "The main findings were that KRAS mutation was associated with advanced disease stage, BRAF mutations were mainly found in right colon, PIK3CA was associated with poor tumour differentiation, MSI was more commonly seen in lower disease stage, larger and more poorly differentiated tumours." (PMID 25884297, 2015). "Interestingly, any tumor but one with PIK3CA mutation additionally carried simultaneous HRAS mutations pointing to the parallel activation of the two major receptor tyrosine kinase downstream signaling pathways, a finding not reflected in previous studies." (PMID 26053092, 2015). "Recently, based on a localized surface plasmon resonance (LSPR) and the coupling plasmon mode of AuNPs, a strategy for the one-step dual detection of tumor-specific mutations (E542K and E545K) and methylation of circulating tumor DNA (ctDNA) of PIK3CA gene has been reported." (PMID 26343676, 2015). "Additionally, two cases (40%) of EMC showed PIK3CA mutations, with one tumor carrying two simultaneous PIK3CA mutations in codon 1049 and in codon 111, both having been described before." (PMID 26053092, 2015). "In this study, we utilised ddPCR to determine whether circulating tumour DNA can be used as an alternative source for PIK3CA mutation analysis in patients with metastatic biliary cancer." (PMID 26498688, 2015). "Furthermore, patients whose tumors have PIK3CA mutations show higher response rates to PI3K/AKT/mTOR inhibitors than do patients whose tumours lack PIK3CA mutations, suggesting that this signaling pathway is a promising therapeutic target for this disease." (PMID 26148118, 2015). "Besides PIK3CA gene, eight of these mutations were observed in independent tumor samples in the replication stage." (PMID 26870154, 2015). "Mutations in KRAS and BRAF are mutually exclusive, but KRAS and PIK3CA mutations may coexist within the same tumor." (PMID 25361007, 2014). "Genotyping for PIK3CA exon 9 mutations was successful in 488 ERα-positive tumor samples." (PMID 24467828, 2014). "Mutations in BRAF or PIK3CA showed a significant correlation with tumor location." (PMID 25367198, 2014). "In the case of PIK3CA mutation, this combination was required to induce tumor regression." (PMID 24451154, 2014).
tumor (continued). "Interestingly, the FFPE sample of Patient 12’s primary tumor was wild type, but a tissue section of her lung metastasis also showed the PIK3CA exon 9 mutation." (PMID 24947048, 2014). "More recently, observational data has suggested that the tumor PIK3CA mutation or high tumor COX2 expression may serve as useful biomarkers for aspirin benefit." (PMID 25250815, 2014). "At least one PIK3CA mutation was detected in 25 tumours (29%)." (PMID 24981670, 2014). "Our data showed that BRAF and PIK3CA mutations were related to tumor site." (PMID 25367198, 2014). "Mutations were discovered in 23% of EC tumor, with PIK3CA/mTOR being the most frequently mutated." (PMID 24859412, 2014). "Loss of ARD1A expression is therefore an early event in ovarian clear cell carcinoma and is often associated with PIK3CA mutations (P = 0.013) that could initiate tumour development." (PMID 24804229, 2014). "PIK3CA mutations (both exon 9 and exon 20) were associated with low tumor grade." (PMID 24467828, 2014). "Interestingly, significant increases in tumor angiogenesis have also beenreported to be associated with oncogenic PIK3CA activity." (PMID 25192370, 2014). "The tumor was resistant to PI3K/mTOR pathway inhibitors despite harboring a PIK3CA mutation." (PMID 23502469, 2013). "Whole exome sequencing performed in tumor tissue obtained at the time of progressive disease demonstrated a somatic gain-of-function PIK3CA mutation (H1047R) as well as a CDKN2A aberration, which may have contributed to eventual resistance to treatment." (PMID 23470635, 2013). "Insulin-independent growth of PIK3CA H1047R-mutated tumor cells is inhibited by metformin in vitro." (PMID 23986086, 2013). "All tumours with PIK3CA mutation showed differences in some downstream pathway members." (PMID 23971979, 2013). "This study is the first to reveal that, remarkably, the isogenic conversion of a PIK3CA-wild-type tumor into a PIK3CA H1047R-mutated tumor is sufficient to promote sensitization to the anti-cancer activity of metformin in an in vivo model of metastatic colon cancer." (PMID 23986086, 2013). "One BRAF mutation, p.Val471Ala, occurred in a tumor also carrying a PIK3CA p.His1047Arg mutation." (PMID 23548132, 2013). "In our series, only 5 tumours with exon 20 PIK3CA mutations were detected." (PMID 23374602, 2013). "PF-04691502 demonstrated antitumor activities in ovarian and glioblastoma tumor xenograft models derived from cancer cell lines carrying either a PTEN deletion or PIK3CA mutation and in a genetically engineered mouse model of ovarian cancer driven by a Kras mutation and Pten deletion." (PMID 23826249, 2013). "We found PIK3CA mutations in 17% of the tumours, unrelated with trastuzumab clinical benefit." (PMID 22454081, 2012). "The primary tumor also harbored a PIK3CA mutation in a small subset of cells." (PMID 22536362, 2012). "Moreover, recent mouse models have reported tumor formation following expression of Pik3ca mutations in mammary cells." (PMID 22666336, 2012). "Furthermore, an oncogenic hotspot mutation in the pleckstrin homology domain (PHD) of AKT1 is present in several tumor entities, albeit at a lower frequency than PIK3CA mutations." (PMID 22363598, 2012). "As we also identified in CRC explants that some tumors with a PIK3CA mutation appear to be more resistant to saracatinib, it is likely that other genetic aberrations are more important at driving tumor growth in this patient's tumor." (PMID 23342270, 2012). "Similar to univariate analysis, after adjustment, PIK3CA amplification was still significantly associated with higher mortality (OR = 3.50, 95% CI = 1.36-9.00; P < 0.05), and PIK3CA mutations remained positively associated with tumor differentiation (OR = 5.53, 95% CI = 0.65-47.4)." (PMID 22292935, 2012).
tumor (continued). "However, PIK3CA amplification was associated with a significantly increased risk of cancer-related death, and positively associated tumor differentiation." (PMID 22292935, 2012). "Somatic mutations of PIK3CA may coexist with either KRAS or BRAF mutations within the same tumor, but KRAS and BRAF mutations appear to be mutually exclusive." (PMID 22931052, 2012). "PIK3CA Exon9 mutation was seen in only one (1.7%) out of 58 tumor tissues tested." (PMID 22586484, 2012). "Mutations in the oncogenes B-Raf and PIK3CA (phosphoinositide-3-kinase) may also influence cetuximab response, highlighting the need for a sensitive, accurate and quantitative assessment of tumour mutation burden." (PMID 21712828, 2011). "In addition, we explored differences in PIK3CA SNP associations in the combined data set by tumour subtype." (PMID 22033276, 2011). "The correspondence of certain cancer mutations in PIK3CA to those found in normal paralogs suggests that selection pressures in the tumor might limit the range of acceptable amino acid changes." (PMID 21208444, 2011). "Tumour DNA was then analysed by dideoxy sequencing for mutations in K-Ras exons 1, 2 and 3 (including the hotspot codons 12 and 13 (exon 1), 61 (exon 2) and codon 146 (exon 3)), PIK3CA (exons 9 and 20) and B-Raf (V600E)." (PMID 21712828, 2011). "In addition, K-Ras, B-Raf and PIK3CA mutation burden ranged from 11 to 99%, 12 to 65% and 14 to 54% of cells, respectively, highlighting marked inter-tumour heterogeneity in mutation burden." (PMID 21712828, 2011). "Recently, one study has shown that PIK3CA mutations may carry prognostic information in tumor stages I–III." (PMID 21103049, 2010). "The dependence of PIK3CA mutations on other signalling components is in keeping with the fact that the genetic background in which tumours develop may require and select specific altered activities of p110-alpha." (PMID 20398348, 2010). "Activating mutations in the gene coding for p110α (PIK3CA) have been found in many human cancer types, including tumors of the colon, brain, ovary, breast, liver, and stomach, and could at least partially explain pathway up-regulation in these neoplasms." (PMID 20671809, 2010). "One recurrent tumor contained two different PIK3CA mutations (E542K and E545K)." (PMID 21072204, 2010). "Thus, in sample 2244 there were fewer PIK3CA mutant alleles in the lymph node than in the primary tumor." (PMID 20233444, 2010). "We and other have shown that the PIK3CA gene is mutated in many tumour types, including GBM." (PMID 19461960, 2009). "One PIK3CA mutation was found in a tumor that also contained a KRAS mutation." (PMID 17487277, 2007). "PIK3CA mutations resulted in attenuation of apoptosis and facilitated tumor invasion." (PMID 19384426, 2007). "PIK3CA was the only gene with somatic (i.e.,tumor-specific) mutations." (PMID 19384426, 2007). "It will be useful and interesting in the future to explore whether PIK3CA mutation is correlated with tumor grade status." (PMID 16168105, 2005). "Furthermore, targetable mutations in KRAS or PIK3CA may affect tumor recurrence and survival in patients with BTCs." (PMID 41301905, 2025). "Thus the high prevalence of PIK3CA mutations may have been underestimated in previous studies because of limited hotspot analysis and single‐sample testing per tumor." (PMID 40489430, 2025). "PIK3CA in our study, which is a common oncogene, exhibited a high mutation frequency in various cancers, and its mutations may have a critical impact on tumor progression and treatment response." (PMID 40270962, 2025). "Furthermore, this tumor also carried a PIK3CA mutation and ERBB2 (HER2) amplification." (PMID 41230344, 2025). "Additionally, these mutations activate tumor-associated fibroblasts (CAFs) and skew macrophages toward the M2 phenotype (TAMs), which collectively suppress T cell infiltration and function, rendering PIK3CA-targeted monotherapy ineffective clinically." (PMID 41281644, 2025).